RHOA (ras homolog family member A)
Diseases named in the same sentence as RHOA in open-access papers (continued):
Sharing a sentence is not in itself a finding about the gene and the disease.
melanoma (continued). "According to these findings, we conclude that CREPT promotes melanoma cell migration and actin filament/focal adhesion formation through RhoA activation." (PMID 31877646, 2019). "Further, we show that CREPT enhances melanoma progression through upregulating and activating Ras homolog family member A (RhoA)-induced actin organization and focal adhesion assembly." (PMID 31877646, 2019). "In the highly motile HT168-M1 melanoma cells, where hypoxia increased the mRNA and protein expression of the three small G-proteins and increased the RhoA activation, HIF-1α silencing reverted these changes." (PMID 28562340, 2017). "ROCK2 functions as a key downstream effector of RhoA small GTPase to play a critical role in the oncogenesis of prostate, bladder, fibrosarcoma, melanoma, liver and lung cancer." (PMID 27229528, 2016). "We next confirmed the well-known antiproliferative effects of UV radiation on melanomas and the potential role of RhoA modulation in this process." (PMID 26823948, 2016). "Our results agree with previous studies that show the crucial role of RSK1 in the migratory phenotype of epithelial or melanoma cells, promoting migration through RhoA inhibition." (PMID 27487136, 2016). "Although the SMAD-dependent induction of RHO GEFs has been described in other studies, how TGFBR1 directly activates RHOA in melanoma cells in a SMAD-independent manner is unclear at present." (PMID 27835901, 2016). "Altogether, these data show that RhoA positively controls transcriptional levels of ectopic CD70 in human melanoma cells." (PMID 26828592, 2016). "The multiple DNA lesions promoted by UV radiation are well known; therefore, we next explored another potential correlation between DNA damage and RhoA activity in MeWo melanoma cells." (PMID 26823948, 2016). "SB-431542 treatment reduced levels of active-GTP bound RHOA, while transfection of melanoma cells with the exoenzyme C3 transferase to inhibit RHOA mimicked the effect SB-431542." (PMID 27835901, 2016). "Hyperactivity and over-expression of RhoA and hyper-activated mutated BRAF have been observed in human cancers, including melanoma." (PMID 26828592, 2016). "Altogether our experiments show that the expression of CD70 in melanoma cells is under the control of RhoA and the MAPK pathway." (PMID 26828592, 2016). "Altogether these results demonstrated that RhoA and MAPK pathways are associated in positive and transcriptional regulation of CD70 expression in melanoma." (PMID 26828592, 2016). "We have shown that specific loss of PAK4 expression concomitantly reduces the invasive potential of melanoma cells and increases the level of RhoA activity." (PMID 27765920, 2016). "In a previous study, we showed that RhoA/ROCK pathway inhibition induced the overexpression of membrane FasL in B16F10 melanoma cell line." (PMID 26236689, 2015). "The release of RhoA from its inhibitory interaction with RhoGDI led to both unregulated RhoA activity and enhanced melanoma cell motility accompanied by remodelling of the cytoskeletal structure." (PMID 25685061, 2015). "In the context of melanoma, somatic splice-site mutation of TMEM216 suggests potential tumor suppressor function and sets the RHOA/GNA12 pathway apart from the Gs-protein/MAPK pathway by mutual exclusivity of TMEM216 towards known oncogenes NRAS and RAC1." (PMID 25600636, 2015). "Other researchers demonstrated that RhoA and RhoC were also over-expressed in highly metastatic melanoma cells." (PMID 25671570, 2015). "Overexpression or knockdown of Swiprosin-1 modulated migration and invasion of B16F10 melanoma cells through Rac1 and RhoA signaling pathways." (PMID 26079945, 2015). "An in vitro study with a single BRAF-mutant melanoma line showed that BRAF-inhibitor treatments were associated with reduced expression of RND3, an antagonist of RHOA activation, and elevated RHOA-dependent signaling." (PMID 24743024, 2014).
melanoma (continued). "The effect of small GTPases, such as Rac1 and RhoA, on the morphology of B16 melanoma cells treated with narrow-band UVB radiation was investigated." (PMID 24649261, 2013). "The role of Rac1 and RhoA in dendrite formation by human melanocytes and melanoma cells was defined by several studies." (PMID 24649261, 2013). "The regulation of cytoskeletal reorganization and migration by RhoA in melanoma cells in response to the chemokine CXCL12 (SDF-1), has previously been described." (PMID 24069584, 2013). "Accordingly, RND3 expression and suppressed RHOA signaling appear to be important for normal melanoma cell movement, whereas RND3 downregulation and enhanced RHOA signaling are critical in BRAF-inhibitor treated cells." (PMID 21917148, 2011). "Two previous studies have shown cooperation between RAF and RhoA in epithelial cell transformation and in melanoma progression." (PMID 21943101, 2011). "The requirement for RHOA in the 3-D invasive outgrowth of melanoma spheroids in the presence of PLX-4720 was then evaluated." (PMID 21917148, 2011). "It is also noteworthy that in a limited number of PDTXs models that were developed by the implantation of human melanoma specimens, following surgical removal from patients tumour into an NSG mouse, the combined opposite targeting of p110δ PI3K and RhoA also abolished melanoma progression." (PMID 38182748, 2024). "Interestingly, it was argued that small GTPase RHOA signaling is responsible for the potential NAC-induced melanoma cell migration, which is in fact another Nrf2-dependent mechanism." (PMID 35892873, 2022). "Furthermore, the activity of SEMA6A/RhoA/YAP axis is induced by dual BRAF/MEK inhibition by dabrafenib+trametinib and, in an environmental-mimicking condition of melanoma cells and fibroblasts co-culture, is associated with reduced targeted therapy efficacy." (PMID 35440004, 2022). "Interestingly, combined inhibition of basal PKC and RhoA effectively impaired MARCKS activity in BRAFi-R melanoma cells." (PMID 36551563, 2022). "However, these authors did not directly analyze RhoA activity but only phosphorylated myosin light chain-2 (p-MLC2) as a presumed marker for RhoA activation in BRAFi-R melanoma cells." (PMID 36551563, 2022). "Our results indicate that the increased basal levels of RhoA and PKC signaling constitute independent mechanisms of MARCKS activation in BRAFi-R melanoma cells and that combined inhibition of RhoA and PKC signaling is an effective means of inhibiting MARCKS activity." (PMID 36551563, 2022). "In summary, using a drug repurposing screening approach, we have identified acquired pharmacological vulnerabilities to compounds that result in mitotic disruption in three different poorly differentiated BRAFi resistant human melanoma cell lines which also exhibit enhanced RhoA/C signaling." (PMID 35444937, 2022). "In addition, NX-5 has the potential to have similar inhibitory effects as Cdc42 inhibitor, Rac1 inhibitor, and RhoA inhibitor in human melanoma cell lines." (PMID 34201921, 2021). "Therefore, dual targeting of both WNT5A and RhoA signaling is more effective in inhibiting the invasion of these melanoma cells than targeting either of these signaling molecules alone." (PMID 33969605, 2021). "Moreover, we confirmed that PKC-ι stimulates Par6 and induced deprivation of RhoA to stimulate EMT in melanoma cells." (PMID 33525953, 2021). "Another study highlighted that FASL expression is regulated by RHOA, which could be important for melanoma cells to escape immune surveillance." (PMID 34503171, 2021). "Additionally, NX-5 (20 μM) treatment significantly decreased the mRNA and protein expression levels of Cdc42, Rac1, and RhoA in melanoma cells compared with the untreated group (p < 0.001 and p < 0.05, respectively)." (PMID 34201921, 2021). "RhoA has also been found to be involved in cell mobility in B16F10 melanoma cells." (PMID 34201921, 2021).
melanoma (continued). "In conclusion, dual WNT5A and RhoA targeting could offer a more effective strategy for blocking melanoma cell invasion." (PMID 33969605, 2021). "In contrast to RAC1, no mutations in RHOA have been detected thus far in melanoma; still, low expression of RHOA was reported to be associated with a poorer prognostic in a cohort of melanoma patients." (PMID 34503171, 2021). "Likewise, the inhibition of the RHOA GEF-H1 by a microRNA (miR-194) suppresses RHOA activation and consequently melanoma cell proliferation and invasion." (PMID 33072757, 2020). "This prompted us to directly test whether RhoA-ROCK signaling is also involved in WNT5A-mediated phosphorylation of MARCKS in melanoma cells." (PMID 32033033, 2020). "We identified that Ras and RhoA were the targets of ropivacaine in melanoma cells." (PMID 32085741, 2020). "In conclusion, we have demonstrated a direct inhibitory effect of ropivacaine and lidocaine but not bupivacaine on melanoma cells, which are associated with sodium channel-independent inhibition of Ras and RhoA signaling." (PMID 32085741, 2020). "Most notably, our 3D approach showed that invasive melanoma cells are featured by high plasticity, with cells capable of modulating either RhoA or Rac1 small GTPases and thus adopting two alternative modes of invasion: amoeboid (rounded) or mesenchymal (elongated), respectively." (PMID 33202906, 2020). "Furthermore, WNT11 stimulated RhoA activity and downstream Myosin II levels in melanoma cells, but this effect was lost when DAAM1 was silenced." (PMID 33082334, 2020). "In addition to CDC42 and RAC1 GTPases, RHOA is also part of molecular networks crucial for the control of melanoma proliferation, migration, and invasion." (PMID 33072757, 2020). "Thus, further studies employing murine models and using larger cohorts of patients should be performed to clarify the impact of RHOA expression in melanoma aggressiveness and progression." (PMID 33072757, 2020). "Indeed, it was described that CREPT promotes melanoma progression via RHOA upregulation and activation." (PMID 33072757, 2020). "A similar mechanism has been demonstrated in melanoma cells through balancing Cdc42/RhoA activity." (PMID 33178698, 2020). "EphrinB2 has been previously reported to activate RhoA-ROCK signalling in melanoma cells." (PMID 31366886, 2019). "Since mTORC1, NF-κB, and ERK1/2 signaling are important in cell apoptosis, we examined whether SMG-enhanced apoptosis is regulated via these signals controlled by FAK/RhoA in BL6-10 melanoma cells under clinostat-modelled SMG-condition." (PMID 29986550, 2018). "Phosphorylation of RhoA at S188 leading to its inactivation may also contribute to the reduced melanoma cell migration." (PMID 29435180, 2018). "Increased phosphorylation of RhoA induced by activation of PKG may also contribute to reduced migration ability of the SkMel28 melanoma cell line when treated with cGMP analogues." (PMID 29435180, 2018). "Moreover, Zhang and colleagues demonstrated that in endothelial cells RacGAP1, by activating RhoA, induced junction breakdown with consequent increase of permeability promoting melanoma cells transendothelial migration." (PMID 28680152, 2017). "QPCR results indicated that the expression of RhoA, RhoB and RhoC reduced in melanoma cells." (PMID 28404912, 2017). "We now find that PAK4 depleted melanoma cells exhibit elevated levels of RhoA activity." (PMID 27765920, 2016). "Thus, the effect of HDACi on melanoma cell invasion is likely the result of a combination of several modifications in cell homeostasis in addition to apopotisis, N-cadherin induction or RhoA inhibition." (PMID 27549189, 2016). "Rho GTPases activity is central to melanoma cells, and indeed we have previously shown that RhoA inhibition induced the up-regulation of several immune-interacting molecules including MHC Class-I, CD80/CD86 costimulatory molecules and FasL, which like CD70 belongs to the TNF superfamily." (PMID 26828592, 2016).
melanoma (continued). "Since Rho GTPases are involved in tumor mobility and that we had previously shown that RhoA regulates the expression of another member of the TNF family (FasL) in melanoma cells, we tested for potential roles of Rho GTPases in the regulation of CD70 expression." (PMID 26828592, 2016). "According to the present study, the use of HDACi in melanoma patients could facilitate metastasis through the up-regulation of N-cadherin and the inhibition of RhoA activity." (PMID 27549189, 2016). "We also observed that WISP-1 inhibited phosphorylation of RhoA/Rac1/CDC42 in C8161 melanoma cells." (PMID 27813493, 2016). "However, the involvement of RhoA in melanoma cell metastasis following exposure to UV light deserves further exploration and understanding." (PMID 26823948, 2016). "The RhoA/Rac1 ratio in the presence of aODN and aODN + inhibitor cocktail conformed to the classical amoeboid pattern indicating a prevalence of RhoA activity in prostate cancer cell lines, while it showed smaller variations with respect to controls in melanoma cell lines." (PMID 24681666, 2014). "By using a multidisciplinary approach, we identified four different treatments able to induce MAT in melanoma cells: EphA2 overexpression, Rac1 functional inhibition using its RacN17 dominant negative mutant, stimulation with Ilomastat or treatment with the RhoA activator Calpeptin." (PMID 24690323, 2014). "It has been reported that overexpression of RhoA increases tumor metastasis in human melanomas." (PMID 20843370, 2010). "We uncovered that the RhoA-myosin II pathway may underlie the YAP enhanced negative durotaxis of melanoma cells." (PMID 36428972, 2022). "However, this suppressive effect appeared to be less pronounced in the RhoA-deficient MeWo-RhoA-N19 clones, and this result supports the hypothesis that the inhibitory effects of UV radiation on melanoma cell invasion are partially dependent on RhoA activity." (PMID 26823948, 2016). "Thus, the cross talk between RhoA activity and genomic stability may suggest this GTPase as a potential target for the sensitization of melanomas to radio-chemotherapies for cancer treatments." (PMID 26823948, 2016). "Indeed, in response to a protease inhibitors-rich milieu, prostate and melanoma cells activated an amoeboid invasion program connoted by retraction of cell protrusions, RhoA-mediated rounding of the cell body, formation of a cortical ring of actin and a reduction of Rac-1 activation." (PMID 24681666, 2014). "It was hypothesized that Rac-dependent Rho activation in response to narrow-band UVB irradiation may serve as a negative feedback to avoid exorbitant dendrite extension promoted by the activated Rac1, according to the role of RhoA activation in dendrite retraction in B16 melanoma cells." (PMID 24649261, 2013). "Thus, the elevated Src activity in the highly invasive metastatic melanoma cells is required for effective αvβ3-mediated invasion and functions in part to limit RhoA activity, which may favor a more migratory phenotype." (PMID 19400942, 2009). "Activation of the RHOA, CDC42, and GSK3β enzymes coordinates the actin–microtubule system to enable saltatory migration of melanoma cells along myelinated tracts." (PMID 41463339, 2025). "The melanoma cells then bind to the endothelial cells using α4β1, αvβ3, and α6β4 integrins and initiate signaling through the FAK-SRC, PI3K-RAC1, and RHOA-ROCK pathways, which lead to the polarization of the cytoskeleton and cycling of focal adhesions." (PMID 41463339, 2025). "S-μg significantly reduces migration in murine BL6-10 melanoma cells by more than 50%, coinciding with the suppression of FAK and RhoA activity." (PMID 40940834, 2025).
melanoma (continued). "In this work, we demonstrate that a combined treatment approach consisting of suppressed p190RhoGAP expression (leading to constantly increased activity of RhoA) into tumours and inactivation of p110δ PI3K in macrophages blocks melanoma and SCC progression." (PMID 38182748, 2024). "Our work shows that a treatment approach consisting of suppressed p190RhoGAP expression into tumours, which keeps RhoA active, combined with inactivation of p110δ PI3K in macrophages almost totally blocks melanoma and SCC progression." (PMID 38182748, 2024). "Here we show that the development and metastasis of melanoma and SCC cancers can be blocked by a combined opposite targeting of RhoA and p110δ PI3K." (PMID 38182748, 2024). "It was demonstrated that melanoma cells exposed to s-μg revealed an increase in apoptosis, alterations of the cytoskeletons, reduced focal adhesions, and the FAK/RhoA signaling pathway." (PMID 37048115, 2023). "Our analysis revealed that RhoA as well as three PKC isozymes (PKCα, PKCε, and PKCι) exhibited increased activity in BRAFi-R melanoma cells." (PMID 36551563, 2022). "Our study highlights important regulatory roles of elevated basal RhoA and PKC activity in mediating MARCKS activation in BRAFi-R melanoma cells." (PMID 36551563, 2022). "In BRAF-mut melanoma cells, SEMA6A coordinates actin cytoskeleton remodeling by the RhoA-dependent activation of YAP and dual BRAF/MEK inhibition by dabrafenib+trametinib induces SEMA6A/RhoA/YAP axis." (PMID 35440004, 2022). "Mechanistically, we show that in BRAF-mut melanoma cells, SEMA6A remodels actin cytoskeleton by activating the RhoA-YAP axis." (PMID 35440004, 2022). "The noncanonical EPHA2 promoted a switch from RAC1 to CDC42 (and RHOA) to increase the invasion and PI3K-dependent p-MLC2 levels in therapy-naïve melanomas." (PMID 35159327, 2022). "We believe that our study is the first to define RhoA and PKC as parallel and independent regulators of MARCKS activity in BRAFi-R melanoma cells." (PMID 36551563, 2022). "Our previous reports on melanoma confirmed that TGFβ stimulated Smad2/3 and Par6/PKC-ι/RhoA pathways stimulated the expression of PKC-ι along with Vimentin." (PMID 33525953, 2021). "Inhibition of the RHOA effector ROCK via the treatment of mice with the Y-27632 compound impairs the growth and invasion of B16 melanoma cells following their transplantation." (PMID 34503171, 2021). "It has been shown that RhoA-ROCK signaling is essential for MAT, and that inhibition of this pathway reduces metastasis in melanoma, colorectal, and triple negative breast cancer." (PMID 29743635, 2018). "Taken together, our observations indicate that SMG inhibits focal adhesions, leading to inhibition of signaling FAK and RhoA, and the mTORC1 pathway, which results in activation of the AMPK pathway and reduced melanoma cell proliferation and metastasis." (PMID 29491429, 2018). "In melanoma and glioblastoma cells, MerTK inhibition mediated abrogation of migration and invasion by altering signaling through total and phosphorylated FAK, RhoA, and total and phosphorylated myosin light chain 2 (MLC2)." (PMID 29554921, 2018). "Taken together, our observations determine that SMG inhibits focal adhesions, leading to reduced melanoma cell proliferation and metastasis via the modulation of the FAK/RhoA-regulated mTORC1 and AMPK pathways." (PMID 29491429, 2018). "Rho inhibitors disrupt the WRAMP complex in human melanoma cells and IQGAP1 is known to interact with RhoA." (PMID 29240845, 2017). "T. Boon for the human melanoma cell lines, Dr. B. Richardson for the CD70 Luc reporter promoter, and Dr. A. Olichon and Cathy Bouchenot for the RhoA-coding adenovirus." (PMID 26828592, 2016). "Our results showed that RhoA and MAPK pathway cross-talk to positively regulate melanoma-expressed CD70." (PMID 26828592, 2016).